CHCHD6 (coiled-coil-helix-coiled-coil-helix domain containing 6)
Description:
Component of the MICOS complex, a large protein complex of the mitochondrial inner membrane that plays crucial roles in the maintenance of crista junctions, inner membrane architecture, and formation of contact sites to the outer membrane.
Synonyms: CHCM1; MIC25; MGC13016; PPP1R23; MICOS25
Tractability: PROTAC: ubiquitination databases record sites on it; its protein half-life has been measured.
Gene: Protein-coding gene on chromosome 3 (126,704,214 to 126,960,420, forward strand). Ensembl gene ENSG00000159685.
Subcellular location: Mitochondrion inner membrane; Mitochondrion
Subcellular location (Human Protein Atlas): Mitochondria; Cytosol
Pathways (Reactome):
Organelle biogenesis and maintenance: Cristae formation
Gene Ontology:
Molecular function: protein binding
Biological process: cristae formation; DNA damage response; inner mitochondrial membrane organization
Cellular component: MIB complex; MICOS complex; mitochondrial inner membrane; mitochondrion; SAM complex; mitochondrial crista junction
Genetic constraint (gnomAD): Loss-of-function variants: 17 observed, 21.06 expected, observed/expected ratio (o/e) 0.81, 90% interval 0.55 to 1.21. The upper end of that interval is the gene's LOEUF score, 1.21, which puts it in group 5 of 6, group 1 being the genes least tolerant of losing a copy. Missense variants: 266 observed, 251.62 expected, observed/expected ratio (o/e) 1.06, 90% interval 0.96 to 1.17. Synonymous variants: 103 observed, 99.57 expected, observed/expected ratio (o/e) 1.03, 90% interval 0.88 to 1.22.
Homologues: Orthologues: chimpanzee CHCHD6 (98% identical), macaque CHCHD6 (80% identical), rabbit CHCHD6 (72% identical), guinea pig CHCHD6 (68% identical), mouse Chchd6 (68% identical), rat Chchd6 (66% identical), pig CHCHD6 (63% identical), tropical clawed frog chchd6 (48% identical), zebrafish chchd6a (41% identical), zebrafish chchd6b (33% identical), Caenorhabditis elegans chch-3 (17% identical). Paralogues in human: CHCHD3 (32% identical).
Diseases named in the same sentence as CHCHD6 in open-access papers:
CHCHD6 is named in the same sentence as 17 diseases in open-access papers, as found by Europe PMC text mining. Sharing a sentence is not in itself a finding about the gene and the disease. The quoted sentences say what the papers report.
Alzheimer disease (2 papers, 2022 to 2023). A progressive, neurodegenerative disease characterized by loss of function and death of nerve cells in several areas of the brain leading to loss of cognitive function such as memory and language. "Previous studied have implicated the role of CHCHD6 in neurodegenerative diseases such as Alzheimer’s disease." (PMID 36982708, 2023). "The top ranked predicted pathways for CHCHD6 were “protein metabolism,” “mitochondrial protein import,” “immune response,” “metabolism of lipids and lipoproteins,” and “Alzheimer’s disease”." (PMID 36104602, 2022).
amyotrophic lateral sclerosis (1 paper, 2025). Amyotrophic lateral sclerosis (ALS) is a neurodegenerative disease characterized by progressive muscular paralysis reflecting degeneration of motor neurons in the primary motor cortex, corticospinal tracts, brainstem and spinal cord. "Amyotrophic lateral sclerosis (ALS)-linked CHCHD10 is implicated in regulating mitochondrial dynamics and respiratory complex activity, while CHCHD6 (MIC25) participates in the cristae-remodeling MICOS complex." (PMID 39806100, 2025).
cognitive deficits (1 paper, 2022). "Our demonstration that compensation for CHCHD6 deficiency mitigates AD-associated neuropathology and cognitive impairment suggests that stabilization of the CHCHD6–APP axis represents a novel therapeutic target for AD patients." (PMID 36104602, 2022). "We have also demonstrated that neuronal downregulation of CHCHD6 accelerates development of AD neuropathology, whereas neuronal compensation for CHCHD6 loss mitigates AD-like pathology and cognitive deficits." (PMID 36104602, 2022). "Compensation for CHCHD6 loss in an AD mouse model reduces AD-associated neuropathology and cognitive impairment." (PMID 36104602, 2022). "Lastly, we addressed the complementary question of whether compensating for CHCHD6 loss would attenuate AD-like neuropathology and cognitive deficits in APPNL−F−G AD mice." (PMID 36104602, 2022). "Collectively, these data demonstrate that downregulation of CHCHD6 accelerates neuropathology and cognitive deficits in AD mice." (PMID 36104602, 2022). "Our results thus demonstrate that compensation for the loss of CHCHD6 in the hippocampus of rapidly developing APPNL−G−F mice reduced AD-associated pathology and cognitive impairment." (PMID 36104602, 2022). "Moreover, AICD-mediated CHCHD6 gene repression is consistent with the notion that loss of CHCHD6 and related MICOS loss are early molecular events of AD pathogenesis prior to Aβ accumulation and cognitive deficits." (PMID 36104602, 2022).
glaucoma (1 paper, 2023). Increased pressure in the eyeball due to obstruction of the outflow of aqueous humor. "Only one coding SNP, rs2272487, located in exon 4 and identified from the exome sequencing data, in the CHCHD6 gene, was identified with an increased risk of glaucoma medication adherence." (PMID 36982708, 2023). "Of most significant coding variants associated with increased risk of glaucoma medication non-adherence, rs2272487 (CHCHD6), rs7975 (GSTZ1), and rs11591349 (SEMA4G) were identified by MPR80." (PMID 36982708, 2023). "The coding SNP rs2272487 in CHCHD6 that overlapped as measured by both MPR80 and PDC80 groups was identified as having a proportionally higher OR for glaucoma non-adherence." (PMID 36982708, 2023).
neuroblastoma (1 paper, 2022). Neuroblastoma (NB) is the most common solid, extracranial childhood tumor. "Exposure of neuroblastoma cells to toxic Aβ1-42, the APP cleavage product, did not alter protein or mRNA levels of CHCHD6, mitofilin, or CHCHD3." (PMID 36104602, 2022).
Schizophrenia-1 (1 paper, 2023). "Although no stress-induced psychiatry disorder has so far been associated with changes in Chchd6 gene expression, dysfunction of MICOS and OXPHOS impairment were found in neuronal cells lacking Disc1 (disrupted in Schizophrenia-1) gene." (PMID 37978166, 2023).
cancer (4 papers, 2016 to 2025). A tumor composed of atypical neoplastic, often pleomorphic cells that invade other tissues. "Downregulation and overexpression of MIC25/CHCHD6 altered chemosensitivity of cancer cells to genotoxic anticancer drugs indicating its potential as a possible target for cancer therapeutics." (PMID 27479602, 2016).
tumor (1 paper, 2023). "In the TCGA datasets, BC tumor tissue showed elevated gene expression levels of IMMT, CHCHD6, CHCHD3, APOO, and MICOS10 as compared to normal tissue, while the APOOL level was decreased in tumor tissue as compared to normal tissue." (PMID 36899366, 2023).
CHCHD6 also shares sentences with these, for which no sentence is quoted: gastric cancer (1 paper); heart failure (1); Hyperglycemia (1); hyperthyroidism (1); infection (1); Insulin resistance (1); neurodegenerative disease (1); non-alcoholic fatty liver disease (1); steatosis (1).